GLO1 (glyoxalase I)
Diseases named in the same sentence as GLO1 in open-access papers (continued):
Sharing a sentence is not in itself a finding about the gene and the disease.
schizophrenia (17 papers, 2012 to 2025). A major psychotic disorder characterized by abnormalities in the perception or expression of reality. "Several studies have linked the MGO levels, GLO1 activity, and their role in the pathogenesis of various conditions, including schizophrenia, autism, anxiety, depression, sleep disorders, and pain phenotypes." (PMID 40002398, 2025). "One study in a Chinese population showed that the GLO1 promoter containing the rs1781735 T allele had significantly lower activity than the G allele and was associated with the risk of schizophrenia." (PMID 38027126, 2023). "To elucidate the impact of loss of function of GLO1 on the pathogenesis of schizophrenia, we generated Glo1 KO mice and evaluated their behavioral phenotypes." (PMID 34953453, 2022). "We have reported that several patients with schizophrenia have a novel frameshift mutation and SNP in GLO1 that results in reductions in enzymatic activity." (PMID 34953453, 2022). "In this study, we first identified evidence that Glo-1 is associated with dysfunction in the frontal cortex in patients with schizophrenia." (PMID 34790095, 2021). "This research aimed to investigate the role of glyoxalase 1 (Glo-1) polymorphisms in the susceptibility of schizophrenia." (PMID 34790095, 2021). "We demonstrated that a novel functional SNP (rs1781735) in the promoter of the Glo-1 gene is associated with the risk of schizophrenia, and a large proportion of individuals with schizophrenia are homozygous for the rs1781735 T allele." (PMID 34790095, 2021). "An unusual clinical GLO1 deficiency, due to a rare frame shift mutation of GLO1, was associated with high risk of severe schizophrenia." (PMID 34440621, 2021). "To date, the research on the relationship between the polymorphisms in the Glo-1 gene and schizophrenia susceptibility has been reported only in a Japanese population." (PMID 34790095, 2021). "The Glo-1 mutation caused structural alteration of the neurites in the post-mortem human cerebral tissues of patients with schizophrenia." (PMID 34790095, 2021). "This study investigated the effect of Glo-1 on schizophrenia risks at multiple levels, such as genetic variants, transcription, expression, protein function, and phenotypes." (PMID 34790095, 2021). "Next, we identified the T allele of rs1781735, which effectively reduced the transcription activation of Glo-1 and was associated with the reduced RNA expression and enzymatic activity in the antipsychotic-naïve first-episode patients with schizophrenia." (PMID 34790095, 2021). "To further identify the effect of Glo-1 on the risk of schizophrenia and more accurately measure the changes in Glo-1, we attempted to reduce or eliminate the influence of other factors, such as antipsychotic drugs and disease treatment period, on the results." (PMID 34790095, 2021). "In aggregate, this study for the first time demonstrates how the genetic and biochemical basis of Glo-1 polymorphism culminates in the brain function changes associated with increased schizophrenia risk." (PMID 34790095, 2021). "The neurite curvature of the S4 case carrying a frameshift mutation in the GLO1 gene was highest for BA249 but lowest for BA22 among the schizophrenia cases." (PMID 33446640, 2021). "We previously reported that a GLO1 frameshift mutation in a schizophrenia patient result in enhanced carbonyl stress with high plasma PEN levels." (PMID 31591136, 2019). "In the S4 schizophrenia case, the high curvature and short radius of the neurites should stem from the GLO1 frameshift mutation." (PMID 30755587, 2019). "Taken together, these results indicate that the GLO1 loss of function (GLO1 (fs) mutation derived from the schizophrenia patient and the engineered GLO1 (−/−) mutation) impaired the cellular development of iPS cells because of the enhanced carbonyl stress." (PMID 31591136, 2019).
schizophrenia (continued). "The schizophrenia case with the highest neurite curvature carried a frame shift mutation in the GLO1 gene, suggesting that oxidative stress due to the GLO1 mutation caused the structural alteration of the neurites." (PMID 30755587, 2019). "In this study, we revealed cellular deficits in neurosphere formation under carbonyl stress in iPS cells from a schizophrenia patient with the GLO1 frameshift mutation." (PMID 31591136, 2019). "In humans, genetic studies have implicated polymorphisms in GLO1 in panic disorder, depression, autism, schizophrenia, and restless legs syndrome (RLS)." (PMID 23181072, 2012). "This degeneration may be linked to reduced GLO1 activity, which has also been observed in some patients with Parkinson’s disease (PD), schizophrenia, and amyotrophic lateral sclerosis (ALS)." (PMID 40002398, 2025). "A recent hospital-based case-control study found significant differences in the distribution of GLO1 variation, RNA expression, and enzyme activity between schizophrenia patients and controls, suggesting GLO1 is associated with dysfunction in the left middle frontal gyrus in schizophrenia." (PMID 35893077, 2022). "Previous studies have found that GLO1 expression and MG accumulation in the brain are associated with the pathogenesis of psychiatric disorders, such as anxiety disorder, depression, autism, and schizophrenia." (PMID 35893077, 2022). "The following receiver operating characteristic (ROC) curves analysis showed that Glo-1 could predict the schizophrenia risk (P = 4.75 × 10−6 in mRNA, P = 1.43 × 10−7 in enzymatic activity, respectively)." (PMID 34790095, 2021). "But the molecular mechanism of GLO1 deficiency in pathogenesis of psychiatric disorders including schizophrenia remains largely unknown." (PMID 33966051, 2021). "We reasoned that the pronounced deficits in cellular phenotypes, observed in schizophrenia patient-derived iPS cells with GLO1 frameshift mutation might be contributed by the additional schizophrenia-associated genetic risk factors in the subject." (PMID 31591136, 2019). "Therefore, additional human genetic studies and studies of GLO1 in mice will help establish an association with schizophrenia." (PMID 23181072, 2012). "Considering the molecular mechanism revealed in this study, GLO1 inducers, such as trans-resveratrol and hesperatin, rather than inhibitors and VB6 supplementation may be effective as a new therapeutic strategy for schizophrenia patients with GLO1 dysfunction and VB6 deficiency." (PMID 34953453, 2022). "These combined results indicated that Glo-1 may confer a risk for schizophrenia." (PMID 34790095, 2021). "The previous studies identified downregulated Glo-1 expression in the blood of Japanese patients with schizophrenia, suggesting that the dysregulation of Glo-1 might be related to the molecular causes or consequences of schizophrenia." (PMID 34790095, 2021). "Among these psychiatric patients with carbonyl stress, several of the patients with schizophrenia were found to harbor mutations in the glyoxalase 1 (GLO1) gene with consequent reduction of enzymatic activity, demonstrating that carbonyl stress may also participate in the schizophrenia pathogenesis." (PMID 31583049, 2019). "We have reported that several patients with schizophrenia have a novel heterozygous frameshift P122fs (rs754100427; NP_006699.2:p.Pro122fs) and an A419C SNP in GLO1, resulting in 40–50% and 15–20% reductions in enzymatic activity, respectively." (PMID 34953453, 2022). "We demonstrated that MG accumulated in the brain of Glo1 KO mice with VB6 deficiency (KO/VB6(−)), and that these mice exhibited schizophrenia-like behaviors, such as a sensorimotor deficit in the prepulse inhibition test." (PMID 34953453, 2022). "Research on human genetics and GLO1 in mice can contribute to establishing a link between GLO1 function and schizophrenia." (PMID 36432007, 2022).
schizophrenia (continued). "Next, we sought to develop a novel model for schizophrenia with an add-on treatment of an environmental factor, vitamin B6 (VB6) deficiency, observed in patients with schizophrenia, in Glo1 KO mice." (PMID 34953453, 2022). "We previously found that VB6 levels in the peripheral blood of schizophrenia patients with GLO1 dysfunction were significantly lower than those in healthy controls." (PMID 34953453, 2022). "The rs1781735 TT genotype, which is associated with a low Glo-1 expression in brains, displayed decreased ALFF in the left middle frontal gyrus compared with the G carriers in the patients with schizophrenia." (PMID 34790095, 2021). "Reduced expression of Glo-1 and, thus, increased accumulation of glycated dicarbonyl compounds have been reported in a subclass of schizophrenia." (PMID 34790095, 2021). "We first reported the effect of the Glo-1 gene on the neural function of schizophrenia using a functional SNP (rs1781735) as the proxy." (PMID 34790095, 2021). "Our investigation lays the foundation for a better understanding of the influence of Glo-1 in schizophrenia and provides a referable analysis workflow in imaging genetics research." (PMID 34790095, 2021). "Our investigation improved the understanding of the effect of Glo-1 on schizophrenia and provides a referable analysis workflow in imaging genetics research." (PMID 34790095, 2021). "We can infer that the low expression of Glo-1 implies the decreased neural activity in the left middle frontal gyrus in patients with schizophrenia." (PMID 34790095, 2021). "The ROC curves were constructed to further evaluate the correlation of Glo-1 mRNA and enzyme activity with the diagnosis of schizophrenia." (PMID 34790095, 2021). "In this study, we aimed to investigate the effects of varying the load of carbonyl stress in neurodevelopment with regard to schizophrenia pathophysiology using GLO1-knockout (KO) human induced-pluripotent stem cells (hiPSCs) and GLO1-KO hiPSC-derived neurons." (PMID 33966051, 2021). "Studies in an animal model have shown a reduced GLO1 level in schizophrenia, resulting in an accumulation of methylglyoxal and thus, modification of behavior, e.g., increased anxiety and depressive states." (PMID 32121669, 2020). "The phenotype of the differentiated neurons from GLO1 (−/−) iPS cells, which showed a shortened neurite length, highly resembles the previously reported phenotypes of iPS cells in schizophrenia." (PMID 31591136, 2019). "Recently, it was reported that carbonyl stress was enhanced in a subpopulation of schizophrenia patients due to a decline in glyoxalase I activity." (PMID 25004141, 2014). "The GLO1 gene has also been identified as a locus relevant to schizophrenia." (PMID 37352288, 2023). "Recently, numerous reports have shown that GLO1 expression and MG accumulation in the brain are involved in the pathogenesis of psychiatric disorders, such as anxiety disorder, depression, autism, and schizophrenia." (PMID 34953453, 2022). "Two relevant studies have recently shown that GLO1 plays an essential role in schizophrenia." (PMID 36432007, 2022). "We speculated that the rs1781735 SNP, located in the promoter region of Glo-1, may affect Glo-1 expression and ultimately contribute to the pathogenesis of schizophrenia." (PMID 34790095, 2021). "The most prominent Glo-1 signal intensities were observed in the left middle frontal gyrus, suggesting that Glo-1 is involved in the dysfunction of the left middle frontal gyrus in schizophrenia." (PMID 34790095, 2021). "To maintain the homogeneity in the cohort in this study, we analyzed Glo-1 expression and enzymatic activity in the peripheral blood of antipsychotic-naïve first-episode patients with schizophrenia and a sex-, age-, and education-matched healthy control group from the same community." (PMID 34790095, 2021).
schizophrenia (continued). "Glo-1 protects the nervous system against toxic carbonyl stress, and its reduced expression may play a key role in the etiology of schizophrenia." (PMID 34790095, 2021). "We hypothesized that Glo-1 might affect the brain function of schizophrenia, considering its crucial role in neurodetoxification." (PMID 34790095, 2021). "Given the critical role of Glo-1 in the detoxification of carbonyl stress, we sought to test the hypothesis that Glo-1 is involved in the pathogenesis of schizophrenia." (PMID 34790095, 2021). "Next, we suspected that rs1781735 may affect the Glo-1 mRNA expression and enzymatic activity in the patients with schizophrenia and healthy controls." (PMID 34790095, 2021). "Collectively, these data indicate that rs1781735 is likely a functional SNP, and sequence changes at this site can influence the Glo-1 transcription activation, mRNA expression, and enzymatic activity in both the patients with schizophrenia and healthy controls." (PMID 34790095, 2021). "In the course of schizophrenia, reduced levels of glyoxalase 1 (GLO1) are also observed." (PMID 32121669, 2020). "Several behavioral assays of schizophrenia-like behavior have been proposed, which could be used for studying mice with aberrant Glo1 expression." (PMID 23181072, 2012). "Recently, two studies have suggested a role for GLO1 in schizophrenia." (PMID 23181072, 2012). "Moreover, synchrotron radiation nanotomography of the structures of cerebral tissues of the anterior cingulate cortex revealed that a schizophrenia patient with the frameshift P122fs in GLO1 showed marked differences in the curvature of neurites, compared with healthy controls." (PMID 34953453, 2022). "Based on the evidence that Glo-1 is broadly expressed in the brains and that rs1718735 could be an eQTL for Glo-1, a neuroimaging analysis was further performed to investigate the relationship of Glo-1 and brain function in schizophrenia using rs1781735 as a proxy of Glo-1 expression." (PMID 34790095, 2021). "Based on these findings, we depleted VB6 in Glo1 KO mice by feeding them VB6-lacking diets to develop a mouse model that further recapitulates the pathology of schizophrenia." (PMID 34953453, 2022).
diabetic nephropathy (16 papers, 2014 to 2025). "Glyoxalase 1 (Glo1) plays an important role in maintaining MGO levels with impairment of the rate of MGO detoxification by Glo1 potentially determining susceptibility to diabetic nephropathy." (PMID 32210089, 2020). "Reduction of GLO1 by small interfering RNA is associated with elevated MG-H1 protein adducts and changes indicative of diabetic nephropathy namely an increased mesangial area, a thickened glomerular basement membrane as well as albuminuria." (PMID 28475116, 2017). "Recent functional genomic studies of Glo1 have linked dicarbonyl glycation to the development of diabetic nephropathy." (PMID 25950009, 2015). "In conclusion, two missense, c.102G>T and c.147C>G, and one nonsense c.148G>T SNVs were found in GLO1 in patients of early and severe diabetic nephropathy, the latter being most deleterious, resulting in a truncated protein." (PMID 39336582, 2024). "Based on the discussion above it is evident that there was a need to explore polymorphism in more genes related to renal function like GLO-1, CBR-1, and ACE, and look for any association with the development of early severe diabetic nephropathy." (PMID 38545031, 2024). "An abnormal increase in MG dicarbonyl stress is a representative marker of diabetic kidney disease, which induces downregulation of renal GLO-1 and increasing flux of MG-derived hydroimidazolone (MG-H1) formation." (PMID 39413106, 2024). "Diabetes-induced loss of podocytes in the glomerulus, one of the early hallmarks of diabetic nephropathy, is also attenuated by overexpression of Glo1." (PMID 32210089, 2020). "Our study indicates that L. bicolor recovers MGO-induced metabolic dysfunction and glucotoxicity in diabetic nephropathy by reducing oxidative stress, inflammation, and renal damage by upregulating Glo1 and Nrf2." (PMID 31370192, 2019). "Parallel downregulation of GLO1 expression further exacerbates the formation of MG modified proteins leading to diabetic nephropathy and neuropathy." (PMID 29456458, 2018). "Upregulation of Nrf2 and Glo1 expression is a useful approach to protect against AGEs-induced diabetic nephropathy." (PMID 30223524, 2018). "The expression and activity of Glo1 in the kidney were decreased in experimental models of diabetic nephropathy—streptozotocin-induced diabetes in mice and rats and the db/db diabetic mouse." (PMID 25950009, 2015). "However, it is observed that if GLO-1 is induced, it abolishes the changes that occur in diabetic nephropathy and improves the outcome." (PMID 38545031, 2024). "GLO-1 gene (which encodes glyoxalase-1 enzyme) has not been explored well for an association of its variations with the development of diabetic nephropathy." (PMID 38545031, 2024). "GLO1 KD in non-diabetic mice induced an alteration in glomerular proteins by MG, causing alterations in kidney morphology similar to diabetic nephropathy." (PMID 34440621, 2021). "An answer might already have been found in the several studies in rats which showed convincing evidence for the close involvement of AGEs and GLO-1 in the pathogenesis of diabetic kidney disease." (PMID 28106734, 2017). "In the same study, overexpression of GLO1 protected from diabetic nephropathy." (PMID 28475116, 2017). "The next question was whether an alteration of GLO-1 activity affects the phenotype of diabetic kidney disease." (PMID 28106734, 2017). "Finally, the upregulation of GLO1 and aldose reductase were protective against diabetic nephropathy alterations in diabetic patients suggesting that boosting this system could be a possible therapeutic approach to delay the development of age-related diseases." (PMID 34440621, 2021). "The affected GLO1 and CBR1 enzymes may lead to the rapid progression of diabetic nephropathy." (PMID 39336582, 2024). "Interestingly, knockdown of GLO1 in nondiabetic mice induces kidney pathology very similar to diabetic nephropathy." (PMID 29783710, 2018).
diabetic nephropathy (continued). "Interestingly, GLO-1 knockdown rats have a similar phenotype to diabetic kidney disease, even without streptozotocin injection." (PMID 28106734, 2017).